TRAF6 (TNF receptor associated factor 6)
Diseases named in the same sentence as TRAF6 in open-access papers (continued):
Sharing a sentence is not in itself a finding about the gene and the disease.
viral infection (continued). "As expected, TRAF6 expression was decreased after TRAF6 interfering virus infection, and increased after TRAF6 overexpressing virus infection." (PMID 29038477, 2017). "Biochemically, GPATCH3 was recruited to VISA in a viral infection dependent manner where it disrupts the assembly of VISA/TRAF6/TBK1 complexes." (PMID 28414768, 2017). "Third, RNF166 interacted with endogenous TRAF3 and TRAF6, and these interactions were enhanced upon viral infection." (PMID 26456228, 2015). "The Vago induction pathway is similar to the RIG-I/TRAF-6/NF-κB-mediated interferon activation pathway, which is activated in response to viral infections in mammalian cells." (PMID 24762775, 2014). "Given its essential role in signaling by various receptors involved in the acquired immune system, TRAF6 represents a key molecule in innate and antigen-specific immune responses against viral infection." (PMID 19479062, 2009). "Because no detectable modulatory effect on the part of MyD88 and TRIF were observed during single-PEDV infection, the up-regulation effect of TRAF6 may be the result of direct viral infection." (PMID 36376395, 2022). "Indeed, virus infection causes interaction between USP25 and TRAF3 (or TRAF6), leading to the stabilization of TRAF3 (or TRAF6) and thus allowing for the production of type I IFNs as well as proinflammatory cytokines." (PMID 35008917, 2022). "miR-146a/b, which is increased during viral infections in general, and HIV in particular, has been shown to downregulate the NF-κB pathway by targeting the TNF receptor-associated factor 6 (TRAF6)." (PMID 32211411, 2020). "We next sought to determine how viral infection affects the levels of OTUD1, Smurf1 and MAVS/TRAF3/TRAF6, and whether the regulation signaling of OTUD1-Smurf1-MAVS/TRAF3/TRAF6 occurs during viral infection." (PMID 29734366, 2018). "The role of Smurf1 in regulating TRAF3/TRAF6 protein levels during viral infection remains unknown so far, although Smurf1 was reported to be able to bind to and ubiquitinate exogenous Myc-TRAFs family members in HEK293T cells." (PMID 29734366, 2018). "However, until this point there are few studies that clearly analyzed the dynamics of downregulation of MAVS/TRAF3/TRAF6 proteins during viral infection." (PMID 29734366, 2018). "Here, our results indicate that OTUD1 could utilize Smurf1 to downregulate MAVS/TRAF3/TRAF6 proteins and restrict IFNs production during viral infection." (PMID 29734366, 2018). "However, how viral infection induces some common mechanisms to negatively regulate the stability of MAVS/TRAF3/TRAF6 signalosome remains to be illuminated." (PMID 29734366, 2018). "Finally, the deubiquitinase OTUD1 potently inhibits RLR pathway by utilizing Smurf1-MAVS/TRAF3/TRAF6 signaling at the early stage of viral infection." (PMID 29734366, 2018). "To investigate whether HCG18 exerts its biological effect by modulating the miR-146a-5p/TRAF6/NFκB axis, we repressed or restored the TRAF6 expression by TRAF6 overexpressing or interfering virus infection in NP cells." (PMID 29038477, 2017). "Restore of TRAF6 expression by virus infection reserved the effect of HCG18 on the NP cells." (PMID 29038477, 2017). "Furthermore, HCG18-induced macrophage invasion and osteogenic differentiation were suppressed due to TRAF6 interfering virus infection." (PMID 29038477, 2017). "In addition, upon viral infection, TRAF6 forms a complex with IRF7 together with MyD88, IRAK4, and IRAK1." (PMID 19479062, 2009). "This may be due to reduction of negative feed back that diminishes IFNα mRNA expression after viral infection in Traf6−/− MEF cells." (PMID 19479062, 2009). "Since RLH-induced NF-κB activation requires the RING domain of TRAF6, the polyubiquitination reaction may also be involved in NF-κB activation in response to viral infection." (PMID 19479062, 2009).
viral infection (continued). "Furthermore, the amount of viral C protein after SeV Cm infection of Traf6−/− MEF cells was higher than that in Traf6+/+ MEF cells at all time points tested after virus infection." (PMID 19479062, 2009). "Thus, viral infection directly regulates TRAF6 in theory and should be further investigated." (PMID 36376395, 2022). "In addition, in order to detect whether miR-2187 will inhibit the expression of TRAF6 during viral infection and LPS stimulation." (PMID 33659012, 2021). "During viral infection, MyD88 recruits members of the interleukin-1 receptor-associated kinase (IRAK)-1 and/or -4 to activate transcription factors belonging to the NF-κB and activator protein 1 (AP-1) family via TRAF6 and transforming growth factor beta-activated kinase 1 (TAK1)." (PMID 29789500, 2018). "Given that MAVS is a mitochondrial protein and Smurf1 can regulate MAVS/TRAF3/TRAF6 proteins during RNA virus infection, we speculate that upregulated Smurf1 proteins by viral infection could be able to localize to the mitochondria to interact with the MAVS/TRAF3/TRAF6 signalosome." (PMID 29734366, 2018). "Furthermore, mutations of the binding sites for TRAF2, TRAF5, and TRAF6 on MAVS abolished the ability of MAVS to activate downstream signaling after virus infection, without affecting its ability to form prion-like polymers." (PMID 23951545, 2013). "During viral infection, miR-146a-5p suppresses the production of type-I interferon by targeting not only IRAK2, TRAF6, and IRAK1 but also STAT-1 and IRF-5." (PMID 38787176, 2024). "Taken together, the results demonstrated that HUWE1 and TRAF6 were downregulated during WSSV infection, leading to the increase in apoptosis and ROS levels and resisting the virus infection in the mud crab." (PMID 35107378, 2022). "The expression of UBXN1 is strongly upregulated late during viral infection and it competes with TRAF3/TRAF6 for binding to MAVS (amino acids 455–460), thus blocking MAVS signaling." (PMID 32536927, 2020). "These deubiquitinases can be activated during viral infection, and then stabilize MAVS, or TRAF3, or TRAF6 protein, which finally promotes IFNs production and host antiviral defense." (PMID 29734366, 2018). "Mechanistically, GPATCH3 was recruited to VISA in a viral infection dependent manner and the assembly of VISA/TRAF6/TBK1 signalosome was impaired in GPATCH3-overexpressing cells." (PMID 28414768, 2017). "TLR7, MyD88, TRAF6, IRAK4 and NF-κB p65 mRNA were up-regulated after virus infection (p < 0.01) while down-regulated after oseltamivir and FTA treatment (p < 0.01)." (PMID 27128889, 2016). "For example, it has been shown that miR-146a is upregulated during viral infection in macrophages and acts as a negative regulator of the retinoic acid-inducible gene I (RIG-I)-like helicases by targeting not only IRAK1 but also TRAF6 and IRAK2." (PMID 23028621, 2012). "It is reported that SERINC5 interacts with MAVS and enhances the formation of MAVS polymers at mitochondria after virus infection, which recruits TRAF6, are essential for NF-κB signaling (NF-κB is the transcription for IFN in response to viral infections and immune responses)." (PMID 39902183, 2024). "Intriguingly, USP25 induced by viral infection prevents TRAF3 and TRAF6 from degradation." (PMID 37888853, 2023). "Therefore, we think that at the late stage of viral infection, more signaling molecules take part in the regulation of the MAVS/TRAF3/TRAF6 signalosome, and finally result in the right balance of RLR-MAVS-IFNs signaling." (PMID 29734366, 2018).
viral infection (continued). "In this study, we observed the TLR3/TRIF/RIP-1 pathway also involved in TRAF1, TRAF2 and TRAF3 activation, but not TRAF6 after stimulation by dsRNA or viral infection in the corneal epithelium." (PMID 25754842, 2015). "Although the IPS-1 interaction with TRAF6 provides another link to IKKαβ, the linkage of RIG-I or RIP-1 to TBK1 and NF-κB for production of pro-inflammatory cytokines and anti-viral IFN-β is unclear in viral infections." (PMID 25754842, 2015). "TRAF6, IRAK1 and IRAK2 play major roles in regulation of immune responses during viral infections." (PMID 25083878, 2014). "Given that TRAF6 RING finger is required for NF-κB activation, this observation is consistent with previous reports showing that lack of p50, Rel, RelA or IKKβ barely affected type I IFN production in response to viral infection." (PMID 19479062, 2009). "Besides, silencing of HUWE1 or TRAF6 significantly suppressed the WSSV replication, indicating that these proteins could promote viral infection in the mud crab." (PMID 35107378, 2022). "Interestingly, TRAF6 was also able to activate IRF3 and induce IFNs during viral infection." (PMID 29734366, 2018).
melanoma (35 papers, 2016 to 2026). A malignant, usually aggressive tumor composed of atypical, neoplastic melanocytes. "The expression level of Autophagy Related 16 Like 2 (ATG16L2) was decreased in TRAF6‐deficient melanoma cells." (PMID 37484971, 2023). "We previously found that tumor necrosis factor receptor‐associated factor 6 (TRAF6) is overexpressed in melanoma and benefits the malignant phenotype of melanoma cells." (PMID 37484971, 2023). "Autophagic activity was elevated in TRAF6‐deficient melanoma cells, which contained more autophagosomes." (PMID 37484971, 2023). "Transcriptomic data and real‐time PCR analysis demonstrated reduced expression of autophagy related 16 like 2 (ATG16L2) in TRAF6‐deficient melanoma cells." (PMID 37484971, 2023). "Another protein important to melanoma-associated fibroblast activity is TNF receptor-associated factor 6 (TRAF6)." (PMID 33430277, 2021). "TRAF6-deficient fibroblast-derived conditioned medium had an opposite effect on melanoma, as it led to a decrease in cancer cell migration, invasion, and cell growth." (PMID 33430277, 2021). "The co-regulation system can involve tumor necrosis factor receptor-associated factor 6 (TRAF6), expressed in CAFs’ activated and melanoma cells." (PMID 33036192, 2020). "Given the well-documented role of MMP9 in cancer metastasis and the direct effect of BSG ubiquitination on cell invasiveness in our present study, TRAF6-mediated BSG ubiquitination represents a novel mechanism underlying BSG-dependent melanoma metastasis." (PMID 26769849, 2016). "Since cinchonine was reported as a TRAF6 inhibitor and was found to induce apoptosis and autophagy, the inhibitory role of cinchonine in melanoma cells might be associated with the ATG16L2 pathway." (PMID 37484971, 2023). "Additionally, we show for the first that ATG16L2 is implicated in autophagy and is regulated by the TRAF6/c‐Jun pathway in melanoma cells." (PMID 37484971, 2023). "In addition, TRAF6 induces the activation of fibroblasts to cancer‐associated fibroblasts in the tumor microenvironment, therefore promoting the malignant phenotype of melanoma cells." (PMID 37484971, 2023). "Therefore, the overexpression of TRAF6 is linked with inflammatory disorders and various types of cancers including pancreatic, liver, lung, head and neck, breast, colorectal, prostate, melanoma, and osteosarcoma." (PMID 38004473, 2023). "Additionally, TRAF6 promotes the activation of cancer‐associated fibroblasts in melanoma." (PMID 37484971, 2023). "Aberrant TRAF6 activation contributes to the pathogenesis of multiple malignancies, including colorectal cancer, melanoma, hepatocellular carcinoma, and acute myeloid leukemia, making it a promising therapeutic target for cancer treatment." (PMID 42121919, 2026). "Research has previously demonstrated TRAF6’s upregulation in various tumors and disease conditions, such as autoimmune diseases, liver cancer, and melanoma." (PMID 38921571, 2024). "Melanoma, a highly malignant form of skin cancer, is associated with the overexpression of TRAF6 (TNF Receptor-Associated Factor 6), an E3 ubiquitin ligase that plays a crucial role in signaling transduction." (PMID 39765834, 2024). "TRAF6 in melanoma cells regulates the secretion of FGF19 through the NF-κB pathway, which activates CAFs to facilitate the malignant phenotype." (PMID 39759028, 2024). "Our previous work suggests that TRAF6 is highly expressed in melanoma and enhances its invasion and metastasis abilities." (PMID 37484971, 2023). "We next found that cinchonine, a TRAF6 inhibitor, suppressed melanoma tumor growth by enhancing autophagy and leading to apoptosis through the c‐Jun/ATG16L2 pathway." (PMID 37484971, 2023). "Since we found a significant change in ATG16L2 expression in TRAF6‐knockdown melanoma cells, further investigation of the role of ATG16L2 was deemed highly important." (PMID 37484971, 2023).
melanoma (continued). "The apoptosis rate increased fivefold in melanoma cells after knockdown of TRAF6 (apoptosis rate: 60–80%) compared with that in sh‐Mock cells (10–20%)." (PMID 37484971, 2023). "The overexpression and activation of TRAF6 signaling have been shown to enhance melanoma invasion and metastasis." (PMID 37389738, 2023). "Taken together, these results indicated that cinchonine inhibited the growth of melanoma cells through the TRAF6/c‐Jun/ATG16L2 signaling pathway." (PMID 37484971, 2023). "Our transcriptomic data suggest that knockdown of TRAF6 regulates the autophagy and apoptosis pathways in melanoma cells." (PMID 37484971, 2023). "To gain deeper insights into the impact of TRAF6 on melanoma cell proliferation, we performed ribonucleic acid (RNA) sequencing of SK‐Mel‐5 cells." (PMID 37484971, 2023). "As we previously demonstrated that TRAF6 was overexpressed in melanoma cells, we expressed short hairpin (sh)‐TRAF6 in the human melanoma cell lines SK‐Mel‐5 and SK‐Mel‐28." (PMID 37484971, 2023). "In this study, we found that knockdown of TRAF6 induced both apoptosis and autophagy in melanoma cells." (PMID 37484971, 2023). "Our findings highlight the therapeutic potential of targeting the TRAF6‐c‐Jun/ATG16L2 axis in melanoma treatment." (PMID 37484971, 2023). "In this study, we uncovered that TRAF6 exerts regulatory control over both apoptosis and autophagy in melanoma cells." (PMID 37484971, 2023). "According to the TCGA melanoma cohort, TRAF6 exhibited a significant upregulation at the mRNA level in melanoma tissues compared to normal tissues." (PMID 37389738, 2023). "The results suggested that the cell growth and death pathway class was altered in TRAF6‐knockdown melanoma cells." (PMID 37484971, 2023). "Cinchonine, an inhibitor of TRAF6, suppressed the growth of melanoma cells and exhibited antitumor effects, suggesting that targeting TRAF6 is a promising therapeutic strategy in melanoma." (PMID 37484971, 2023). "Nevertheless, the precise involvement of TRAF6 in the autophagic and apoptotic processes within melanoma cells remains uncertain." (PMID 37484971, 2023). "In this study, we demonstrated that TRAF6 modulated the expression of c‐Jun/ATG16L2, and that knocking down either TRAF6 or ATG16L2 induced apoptosis in melanoma cells." (PMID 37484971, 2023). "Inhibition of TRAF6 using cinchonine effectively suppresses melanoma cell growth by inducing apoptosis and autophagy." (PMID 37484971, 2023). "In conclusion, our study demonstrates that reducing the expression of TRAF4, TRAF5, or TRAF6 significantly improves the sensitivity of human ovarian cancer or melanoma cells to retinoic acid." (PMID 37389738, 2023). "Epigallocatechin-3-gallate has been reported to inhibit growth of melanoma cell through suppressing TRAF6 activity." (PMID 36202787, 2022). "It was shown that conditioned medium collected from fibroblasts overexpressing TRAF6 increased melanoma proliferation, migration, and invasion." (PMID 33430277, 2021). "In melanoma cells, TRAF6 promotes nuclear factor kappa-light-chain-enhancer of activated B cells (NFkB)-dependent release of fibroblast growth factor 19 (FGF19), implicated in the transformation and activation of fibroblasts." (PMID 33036192, 2020). "It is worth noting that although TRAF6 has been shown to regulate apoptosis in other cell types, the mechanisms by which TRAF6 resulted in melanoma cell death is unique." (PMID 32533049, 2020). "TRAF6 is an adaptor protein that mediates protein–protein interactions and is overexpressed in melanoma." (PMID 32397337, 2020). "To this end, we challenged Traf6fl/flFoxp3Cre+ mice and their TRAF6‐competent littermates with aggressive, poorly immunogenic B16 melanomas." (PMID 30886050, 2019). "EGCG treatment blocked the regulation of NF-κB pathway activation by TRAF6 and inhibits melanoma cell growth, invasion and migration." (PMID 30585192, 2018).